LRPPRC (leucine rich pentatricopeptide repeat containing)
Diseases named in the same sentence as LRPPRC in open-access papers (continued):
Sharing a sentence is not in itself a finding about the gene and the disease.
cancer (continued). "Analysis using the cancer genome atlas (TCGA) data showed that the mRNA levels of LRPPRC were significantly increased in 8 out of 10 malignancies, including HCC." (PMID 34671012, 2021). "As one of the m6A regulatory proteins, LRPPRC expression increased in diverse cancer tissues but decrease in normal tissues." (PMID 34650549, 2021). "Several studies have shown that LRPPRC is upregulated in different cancer tissues and cell lines, including prostate, gastric, lung and colon cancer." (PMID 34888254, 2021). "Previous studies have shown that in cancer progression, LRPPRC interacts with Beclin 1 and Bcl-2 and forms a ternary complex to maintain Bcl-2 stability, resulting in the maintenance of mitochondrial homeostasis and mitochondrial function." (PMID 32898195, 2020). "Zou and colleagues investigated a possible connection between autophagy inhibition and LRPPRC involvement in cancer development." (PMID 31064115, 2019). "LRPPRC is abundantly expressed in the side population of lung adenocarcinoma cell lines, where cancer stem cells are enriched." (PMID 31064115, 2019). "For example, LRPPRC is found to be highly expressed and subsequently prevent the apoptosis or induce autophagy in several cancer types." (PMID 28184026, 2017). "EPRS was repeatedly elevated in adenocarcinoma relative to control in 79% of cancer subjects, whereas both LRPPRC and COPG1 were consistently elevated in 76% of subjects." (PMID 27799870, 2016). "Our understanding of the role of LRPPRC on mitochondrial function is scarce, and derived primarily from studies in which wild type LRPPRC was knocked-down in a cancer or liver transformed cell line." (PMID 25835550, 2015). "This also emphasizes the idea that LRPPRC inhibitors could be less toxic to normal cells while eliminating SDHA/LRPPRC-overexpressing cancer cells." (PMID 40563592, 2025). "Moreover, it has been found that the dysregulation of LRPPRC expression affects cancer progression through upstream regulators, interacting partners, and downstream targets." (PMID 41516324, 2025). "Therefore, T-96 can inhibit the malignant phenotype of cancer cells, and this inhibitory effect is dependent on the expression of the LRPPRC protein." (PMID 39744573, 2025). "LRPPRC plays an important role in tumorigenesis, metastasis, and drug resistance by regulating cancer epigenetic modification, signal transduction, cancer metabolism, and cancer immunity." (PMID 41516324, 2025). "High expression of LRPPRC may inhibit NK cell activity, thereby suppressing the immune response and promoting cancer progression." (PMID 37534256, 2023). "To determine whether LRPPRC is correlated with stemness and drug resistance in OC, we examined its expression in cancer stem cell (CSC)-like and cisplatin (DDP)-resistant cells." (PMID 37496051, 2023). "LRPPRC expression was markedly increased in cancer tissue samples relative to benign tissues." (PMID 37496051, 2023). "PSMD14 could enhance cancer cells malignancy through the LRPPRC/Beclin1-Bcl-2/SQSTM1 signaling pathway inducing autophagy." (PMID 36632137, 2023). "In a word, we hypothesized that LRPPRC could impede the activation of immune cells (like CD8 T cells) or mRNA processing to regulate cancer development and progression." (PMID 34650549, 2021). "For instance, the eIF4E/LRPPRC-mediated CRM1 pathway is upregulated in many cancers." (PMID 32383752, 2020). "LRPPRC acts as a regulator of mitochondrial DNA-encoded mRNAs and participates in glucose homeostasis, energy metabolism and nuclear receptor activation and is abundantly expressed in NSCLC adenocarcinoma and other cancers." (PMID 27799870, 2016). "Consequently, we propose that high levels of SDHA and LRPPRC could serve as novel biomarkers of high-OXPHOS tumors to guide personalized cancer therapy." (PMID 40563592, 2025).
cancer (continued). "Correlation analysis between m6A score and m6A regulators in pan-cancer also demonstrated that m6A score could reflect the expression level of m6A regulators in pan-cancer, and the candidate m6A regulator LRPPRC had obvious positive correlation with m6A score in almost all cancer types." (PMID 35069534, 2021). "The expression of both LRPPRC and SDHA was very low in normal fallopian tubes when compared with cancer samples." (PMID 40563592, 2025). "The results revealed that SLC7A11, SLC3A2, RPN1, LRPPRC, and GYS1 were highly expressed in several cancer tissues." (PMID 38271056, 2024). "Reported molecular functions of LRPPRC include cell oxidative phosphorylation (OXPHOS) regulation and cancer stem cells (CSCs) maintenance." (PMID 37452037, 2023). "With regard to cancer, an m6A score based on the expression of IGF2BP2, IGF2BP3, KIAA1429, METTL3, EIF3H, and LRPPRC was reported as an indicator of pancreatic tumor microenvironment status and was a potential biomarker for patients’ prognosis." (PMID 37903783, 2023). "In most cancer types, LRPPRC exhibited the notable upregulation in tumors relative to normal tissues." (PMID 37063837, 2023). "Notably, NDUFA11, OXSM, LRPPRC, NCKAP1, RPN1, SLC3A2, and SLC7A11 were upregulated in cancer tissues, while NDUFS1 showed the opposite trend." (PMID 38213838, 2023). "HNRNPA2B1, HNRNPC, LRPPRC, ALKBH5 showed high expression in almost all cancers." (PMID 35265626, 2022). "Our results revealed that in GBM cancer cells, expression of CD274 (PD-L1), PDCD1LG2 (PD-L2), LGALS9 (Galectin-9), and PVR (CD155) were positively correlated with the expression of multiple m6A regulators, especially YTHDF2, YTHDF3, LRPPRC, METTL3, RBM15B, FTO, and ALKBH5." (PMID 35558067, 2022). "Indeed, a higher LRPPRC expression was found in cancer tissues compared to paired noncancerous regions and in patients with a poor survival rate." (PMID 34888254, 2021). "LRPPRC (leucine-rich pentatricopeptide repeat containing), and Fas-activated serine/threonine kinase (FASTK) are protein families playing a major role in mt-mRNA stability and translation and whose dysregulation is related to diverse pathological processes, including cancer." (PMID 34888254, 2021). "Importantly, our findings revealed that the concomitant overexpression of SDHA and LRPPRC could be considered as novel biomarkers for identifying tumors that rely on high OXPHOS metabolism, offering a potential avenue for tailoring personalized cancer treatments." (PMID 40563592, 2025).
mitochondrial disease (9 papers, 2015 to 2025). "Although pathogenic mutations in the LRPPRC and SLIRP genes cause devastating human mitochondrial diseases, the in vivo function of the corresponding proteins is incompletely understood." (PMID 39087558, 2024). "We applied SILAF to quantify the mitochondrial phosphoproteome of an early-stage leucine-rich PPR motif-containing protein (LRPPRC)-knockdown model of mitochondrial disease that exclusively affects the intramitochondrial synthesis of proteins involved in oxidative phosphorylation (OXPHOS)." (PMID 33640490, 2021). "We applied SILAF to quantify the mitochondrial phosphoproteome of an early-stage leucine-rich PPR motif-containing protein (LRPPRC)-knockdown fly model of mitochondrial disease that almost exclusively affects protein levels of the oxidative phosphorylation (OXPHOS) system." (PMID 33640490, 2021).
infection (3 papers, 2012 to 2021). The state of being infected such as from the introduction of a foreign agent such as serum, vaccine, antigenic substance or organism. "This suggested that LRPPRC interacted with RTCs and PICs during early infection via an association with viral nucleic acids." (PMID 22808186, 2012). "Compared to the 293T.NS cells, an approximately 75% decrease in HIV-Luc transduction was observed for all three of the shLRPPRC cell lines, indicating that LRPPRC expression was critical for efficient infection." (PMID 22808186, 2012). "Infection of the 3.6 and 4.1 cell lines resulted in an impairment in the accumulation of 2-LTR circles in the nuclei of cells, implying that nuclear LRPPRC is necessary for efficient nuclear import of viral DNA." (PMID 22808186, 2012). "To identify which aspect of infection was impaired in the LRPPRC-depleted cells, we assessed reverse transcription, nuclear import, and PIC formation in the LRPPRC depleted cell lines." (PMID 22808186, 2012). "LRPPRC was found to interact with HIV-1 RNA and DNA during early infection." (PMID 22808186, 2012).
neurodegenerative disease (3 papers, 2018 to 2023). A disorder of the central nervous system characterized by gradual and progressive loss of neural tissue and neurologic function. "Oxidative phosphorylation genes specific for HCHWA-D, i.e., not represented in the other neurodegenerative disease categories were the ATP6V subunits, COX14, COX15, LRPPRC, and TCIRG1." (PMID 29706885, 2018).
adenocarcinoma (1 paper, 2016). A common cancer characterized by the presence of malignant glandular cells. "Adenocarcinoma-dependent elevations in LRPPRC were associated with similar increases in STOML2 and PDIA4, which exhibited 2- and 2.3-fold increases in adenocarcinoma relative to control tissue, respectively." (PMID 27799870, 2016). "HYOU1 and NANS were both positively correlated with adenocarcinoma-associated increases in EPRS, which was also positively associated with LRPPRC and COPG1." (PMID 27799870, 2016). "Consistent with our proteomic data, mRNA expression of APEX1, HYOU1, PDIA4, NANS, LRPPRC, EPRS and COPG1 were significantly (Mann–Whitney U < 0.05) higher in adenocarcinoma compared to control whereas mRNA abundance of HBG1, HBG2, HBD, and PTRF were significantly (Mann–Whitney U < 0.05) lower." (PMID 27799870, 2016).
LRPPRC also shares sentences with these, for which no sentence is quoted: cardiovascular diseases (2 papers); cervical cancer (2); infertile (2); venous thromboembolism (2); bladder tumors (1); clear cell renal adenocarcinoma (1); cognitive decline (1); colon cancer (1); developmental delay (1); diffuse large B-cell lymphoma (1); dyslipidemia (1); endometriosis (1); epilepsy (1); Hyperglycemia (1); Hypergonadotropic hypogonadism (1); Intellectual disability (1); intervertebral disc degeneration (1); intracranial aneurysms (1); liver cancer (1); lymphoma (1); malaria (1); male infertility (1); mastitis (1); mitochondrial neurogastrointestinal encephalomyopathy (1); mtDNA depletion syndromes (1); Myocardial fibrosis (1); neurofibromatosis (1); non-alcoholic fatty liver (1); normal tension glaucoma (1); pancreatic adenocarcinoma (1).
A further 10 diseases each share a sentence with LRPPRC in 1 paper.